SOCS2 (suppressor of cytokine signaling 2)
Diseases named in the same sentence as SOCS2 in open-access papers (continued):
Sharing a sentence is not in itself a finding about the gene and the disease.
tumor (continued). "SOCS2 is reported to be highly expressed in HCC, associated with the N6-methyladenosine (m6A) in tumor pathogenesis and progression." (PMID 36159831, 2022). "One of the pairs (ENSGALG00000043746/SOCS2) was excluded from subsequent analysis due to failure of ddPCR analysis for the lncRNA ENSGALG00000043746 in the tumor samples." (PMID 35939448, 2022). "Suppression of SOCS2 was found to induce tumor immune escape by inhibiting the development of Th2 cells and restricting the adaptive anti-tumor immunity of T cells in multiple tumor models." (PMID 34262594, 2021). "As demonstrated by western blot, up-regulation of circNOL10 led to a rise of SOCS2 and E-cadherin protein levels, while a decline of N-cadherin protein expression in tumor tissues." (PMID 33397365, 2021). "Results showed significant upregulated expression of certain genes like Hgf, Hmga1, Rasgrp1, Sh2b2, Socs1, Socs2, and Socs3 in WT mice tumor compared to its ChREBP systemic knockout tumor." (PMID 34685767, 2021). "Overexpression of JMJD1C inhibited tumor growth, but this effect was reversed by the addition of sh‐SOCS2 treatment." (PMID 34586733, 2021). "Regarding SOCS2 expression, a total of 440 studies were considered, among which 27 showed increased expression and 55 showed decreased expression in tumor tissues compared with normal tissues." (PMID 34120621, 2021). "Among the significant DEGs, SOCS2 has been reported as a tumor suppressor and its expression is regulated by the JAK-STAT5 pathway." (PMID 34312374, 2021). "Mechanistically, METTL3 facilitated tumor progression by modulating suppressor of cytokine signaling 2 (SOCS2), RAD52 motif 1 (RDM1) and Snail." (PMID 33879256, 2021). "In their studies, the tumour suppressor SOCS2 was identified to be the direct downstream target of METTL3." (PMID 33090698, 2020). "It has been confirmed that YTHDF2 induced the targeted degradation of the tumor suppressor SOCS2 to promote tumor progressions of HCC, and this regulation was dependent on METTL3-induced m6A modifications." (PMID 33121495, 2020). "This evidence supports that SOCS2 generally limits tumor growth, which is consistent with our conclusion." (PMID 33414813, 2020). "The tumor-promoting effect of METTL3 was also reflected by its activity to mediate YTHDF2-dependent mRNA decay of SOCS2, a suppressor of cancer metastasis." (PMID 33584787, 2020). "The other cluster including RASSF5, RASSF6, STAT1, CEACAM1, BNIP3L and SOCS2 is related to tumor suppression." (PMID 32201535, 2020). "Subsequently, the abundances of p-STAT5, STAT5, p-JAK2, JAK2, and SOCS2 proteins were measured in tumor tissues." (PMID 30988277, 2019). "Statistical analysis with ANOVA multiple comparisons test showed that the expression of NR1H4 and SOCS2 in tumor were lower than normal tissues in two cancer types." (PMID 30787420, 2019). "Relative to normal adjacent tissues, SOCS2 expression was significantly downregulated (P < 0.01) in 86% (80/92) of tumour tissues." (PMID 29559623, 2018). "As the EMT is the initial step of tumour metastasis, these data greatly support the concept of SOCS2-involved lung adenocarcinoma metastasis and reveal a novel biological role of SOCS2 in malignant cancer progression." (PMID 29559623, 2018). "We found substantial changes of both DNA methylation and mRNA expression of CR1, ESR1, PTPN13, and SOCS2 in HCCs compared with paired non-tumor tissues, which is consistent with the results obtained by analyzing the array data in our discovery sample." (PMID 25965583, 2015). "SOCS2 expression increase was confirmed at the protein level in the majority of tumor centers, while its overexpression in the peripheral areas was variable and in general less marked than in the centers." (PMID 26188123, 2015). "In xenografts derived from SOCS2 knockdown cells, we observed a significantly reduced tumor area after 5 days on the CAM." (PMID 24280133, 2014).
tumor (continued). "To confirm a possible anti-proliferative effect of SOCS2 knockdown on tumor growth in vivo, we applied a CAM assay using PC3 shSOCS2-1 or shLuc cells." (PMID 24280133, 2014). "In the present study, we investigated SOCS2 expression patterns in benign and low- and high-Gleason score tumor samples as well as in prostate cell lines." (PMID 24280133, 2014). "Immunohistochemical staining revealed a reduced SOCS2 expression in the tumor cells as well as a significant decrease in the proportion of Ki67-positive cells." (PMID 24280133, 2014). "After adjusting for tumor grade, lymph node, ER and PR status high SOCS2 expression remained an independent predictor for good prognosis." (PMID 17651480, 2007). "Furthermore, SOCS2 expression was significantly higher in normal tissues than in tumor tissues and negatively correlated with the T Stage in patients with HCC." (PMID 39574357, 2025). "This study highlights the important role of HCC‐derived exosomal miR‐500a‐3p in intercellular communication, which may be responsible for HSC activation and tumor aggressiveness via the downstream SOCS2/JAK3/STAT5A/STAT5B regulatory loop." (PMID 39574357, 2025). "SOCS2 has been identified as a strong inhibitor of tumor metastases in HCC." (PMID 39796711, 2024). "Moreover, from clinical data we found that SOCS2 expression was correlated with tumor metastasis and vascular invasion." (PMID 38071211, 2023). "In conclusion, the overexpression of miR-532-3p could suppress proliferation, invasion, and migration of PC cells, as well as tumor formation in nude mice through inhibiting the methylation of SOCS2 by targeting DNMT3A." (PMID 37085288, 2023). "Herein, we detected the expression of SOCS2 in tumor-adjacent tissues and PDAC tissues via IHC." (PMID 36539807, 2022). "Furthermore, the data also showed that SOCS2 mRNA levels were decreased in HCC samples compared with non-tumor samples." (PMID 34990401, 2022). "In the present study, we unveil LINC02362 as a novel tumor-inhibitory lncRNA by directly sponging miR-516b-5p and indirectly increasing the levels of SOCS2, leading to the attenuation of proliferation and metastasis as well as the augment of apoptosis in HCC cells." (PMID 34990401, 2022). "SOCS2 acts as a tumor suppressor that regulates cell fate in many cancers." (PMID 35037826, 2022). "SOCS2 has been proved to act as a pivotal tumor suppressor in various types of cancer." (PMID 34990401, 2022). "Together, circNOL10 exerted tumor-suppressive role in BC through regulating SOCS2." (PMID 33397365, 2021). "SOCS2 expression was significantly lower in BRCA tumor tissues than that in normal samples." (PMID 33397365, 2021). "Moreover, the expression of SOCS genes at different tumor stages were analyzed and the results showed that the higher the clinical stage, the lower were the expression levels of SOCS2 and SOCS3 (p < 0.05)." (PMID 34120621, 2021). "Based on this function, they may be expected to act as tumor suppressors; correspondingly, SOCS2 was downregulated in several cancer types." (PMID 34029637, 2021). "SOCS2 is usually being considered as a tumor suppressor in multiple cancers." (PMID 34312374, 2021). "METTL14 inhibits tumor invasion and metastasis by regulating miR-126 while promoting tumor cell proliferation and migration by regulating suppressor of cytokine signaling 2 (SOCS2)." (PMID 31722709, 2019). "Overexpression of STAT3 plays a key role in tumor proliferation, lots of studies indicated that inhibit the activation of STAT3 is beneficial for cancer treatment, so the expression of SOCS1, SOCS2 may inhibit tumor cell survival." (PMID 30787420, 2019). "Knockdown of NR1H4 can also attenuate the expression level of SOCS1 and SOCS2 after ZINC24469384 treatment, and the decrease of SOCS2 is sharper than SOCS1, These data indicated that SOCS2 may play more important role in NR1H4 induced anti-tumor effects." (PMID 30787420, 2019).
tumor (continued). "Increasing evidences demonstrated that SOCS2 might function as a tumor suppressor in HCC by regulating tumor progression." (PMID 30988277, 2019). "Second, SOCS2 overexpression led to significantly increased tumor growth in vivo." (PMID 29622769, 2018). "SOCS2 knockdown inhibited tumor growth in vitro and in an animal xenograph model." (PMID 29622769, 2018). "However, regulation of SOCS2 by upstream molecules has yet to be clearly elucidated, particularly in tumor cells." (PMID 29622769, 2018). "Here, we show that SOCS2 were significantly downregulated in tumour foci in NSCLC patients." (PMID 29559623, 2018). "SOCS2 was also downregulated in tumor tissues (p < 0.00001)." (PMID 28717245, 2017). "First, SOCS2 downregulation leads to a significantly diminished tumor growth in vivo." (PMID 24280133, 2014). "In primary tumor tissue, SOCS2 expression was positively correlated with the Gleason score, and relapse-free survival was significantly shorter in patients with a high SOCS2 expression." (PMID 24280133, 2014). "Evidence from previous studies point to activated STAT5 as a possible SOCS2, SOCS3 and CIS genes controller and its loss may result in less differentiated and more malignant tumours, and subsequently; poorer prognosis." (PMID 20433750, 2010). "Furthermore, four studies have investigated the tumor-suppressing role of SOCS2 in LUAD." (PMID 35037826, 2022). "Furthermore, knockdown of SOCS2 reversed the tumor-suppressive effect induced by circNOL10." (PMID 33397365, 2021). "Additionally, miR-196b may accelerate tumor cell proliferation, migration, and invasion by targeting SOCS2." (PMID 34605350, 2021). "In addition, SOCS2 has been investigated as molecular targets of many microRNAs in multiple different tumours, including miR‐196a/miR‐196b,39 miR‐49240 and miR‐875,41 suggesting that SOCS2 may form an important regulatory network mediated by miRNAs." (PMID 32536038, 2020). "Taken together, the fact that SOCS2 is frequently deregulated in IL-1β-related cancers indicates that SOCS2 expression and its regulatory functions in DCs may support cancer progression by dampening anti-tumor immune responses." (PMID 31775389, 2019). "Consequently, SOCS2−/− mice showed enhanced tumor surveillance." (PMID 28383049, 2017). "In addition, we could demonstrate that patients with a high SOCS2 expression are more likely to experience biochemical tumor relapse." (PMID 24280133, 2014). "Therefore, high STAT5 activation in the tumor is compatible with higher SOCS2 levels." (PMID 17651480, 2007). "CircNOL10 inhibits mammary tumorigenesis via miR-767-5p-dependent SOCS2 upregulation, which blocks JAK2/STAT5 signaling, thereby impairing tumor growth and metastatic dissemination." (PMID 41601694, 2026). "In HCC, METTL3 promotes tumor growth by regulating oncogenic and tumor-suppressing genes, including SNAIL, YAP1, LINC00958, and SOCS2." (PMID 40302799, 2025). "SOCS2 expression has also been shown to be significantly decreased in HCC and to be related with aggressive tumor development and a poor prognosis in HCC patients." (PMID 38969729, 2024). "Therefore, SOCS2 might exert a tumor-suppressive effect in vitro." (PMID 37085288, 2023). "In seven pairs of specimens from individuals with LIHC, qRT-PCR and IHC analysis revealed high SPP1 expression in tumor tissue, while FLT3, SOCS2 displayed the reverse trend." (PMID 37346073, 2023). "The level of miR-1307-3p was downregulated in tumor tissues treated with RGD-Exo-circDIDO1, while SOCS2 was upregulated subsequently." (PMID 35864511, 2022).
tumor (continued). "NANOG also works together with other stemness factors, such as MYC, OCT4, KLF4, SOX2, SOCS2, or ALDH1A1, to control a set of target genes that have important functions in embryonic stem cells and, plausibly, in tumor cells." (PMID 35104240, 2022). "In our current study, we demonstrated for the first time that circ_0006677 acts as a key tumor suppressor to inhibit NSCLC progression and metabolic reprogramming via mediating the miR-578/SOCS2 pathway." (PMID 34054537, 2021). "Less is known about the roles of SOCS4 than about the roles of SOCS2 and SOCS3 in tumor growth and malignancy." (PMID 34120621, 2021). "In detail, METTL3-mediated m6A modification repressed the suppressor of cytokine signaling 2 (SOCS2), which acted as a tumor suppressor in HCC via YTHDF2-mediated mRNA degradation." (PMID 33593354, 2021). "SOCS2, another member of the SOCS family, displays both oncogenic and tumor-suppressive activities in different human tumors." (PMID 33397365, 2021). "Overall, these findings suggest that WDFY3‐AS2 is tumour suppressor lncRNA that inhibits cell proliferation and invasion by WDFY3‐AS2/miR‐2355‐5p/SOCS2/JAK2/Stat5 signalling pathway in ESCC cells." (PMID 32536038, 2020). "Suppressor of cytokine signaling 2 (SOCS2), a direct downstream target of METTL3, inhibited tumor progression." (PMID 32733807, 2020). "Mechanistically, METTL3 promotes HCC growth and invasiveness by repressing the expression of suppressor of cytokine signaling 2 (SOCS2), a tumor suppressor in HCC, through m6A-YTHDF2-dependent mRNA degradation." (PMID 31921664, 2019). "Alteration of m6A levels participates in cancer pathogenesis and development via regulating expression of tumor-related genes like BRD4, MYC, SOCS2 and EGFR." (PMID 31801551, 2019). "Therefore, we hypothesized that SOCS2 expression is involved in tumor cell growth." (PMID 29622769, 2018). "In this tumor model, METTL3-mediated m6A modification targets suppressor of cytokine signaling 2 (SOCS2), promoting its degradation, in a process dependent of YTHDF2 reader." (PMID 30428628, 2018). "The results demonstrated that UPB1 and SOCS2 were downregulated in HCC tissues (UPB1: p < 0.0001; SOCS2: p < 0.0001), while the expression of RTN3 was increased in tumor tissues (p < 0.0001)." (PMID 28717245, 2017). "Four genes (EPHA7, SOCS2, SYNM, WNK2) are tumor suppressor genes whose hypermethylation is a common mechanism of downregulation." (PMID 28927421, 2017). "UPB1 and SOCS2 exhibited lower expression than the corresponding normal tissues, while RTN3 showed a tendency of increase expression in tumor tissues (p = 0.09)." (PMID 28717245, 2017). "Our data showing the reduced expression of the SOCS2 L163P and C167F SOCS-box and the R73E SH2-domain mutants, which are defective in Elongin C interaction lend support to these hypotheses and is in line with previous data from studies with VHL tumour suppressor SOCS-box point mutations." (PMID 21980433, 2011). "Furthermore, STAT5 expression levels in the primary tumor as determined by immunohistochemisty was associated with better response to endocrine therapy suggesting a possible crosstalk between ER and STAT5, which could be mediated by SOCS2." (PMID 17651480, 2007). "Moreover, SOCS2 and SLC7A11 were expressed oppositely in HCC clinical tissues and tumour xenografts with different radiosensitivities." (PMID 35995846, 2023). "miR-196b may exist as a tumor-promoting factor in ESCC and enhance the proliferation abilities, migration capacities, and invasion potential of ESCC cells by targeting SOCS2." (PMID 34605350, 2021). "In BC, SOCS2 were found to be significantly down-regulated in tumor tissues compared with the corresponding adjacent non-cancerous tissues." (PMID 33397365, 2021). "SOCS2 has been considered as important regulators of the Janus kinase/signal transducers and activators of transcription (JAK-STAT) pathway in various inflammatory and neoplastic diseases." (PMID 33397365, 2021).
tumor (continued). "Moreover, numerous genes modified by m6A have been revealed to play regulatory roles in tumour formation, such as BCL2, PTEN, SOCS2, FOXM1 and HBXIP." (PMID 30031372, 2018). "We next randomly selected 8 genes aberrantly expressed in HCCs that had aberrant DNA methylation (CR1, ESR1, PTPN13, and SOCS2) or SCNA (C8A, CXCL14, ITGA6 and MARCO) to validate the array-based results in an independent sample set consisting 47 HCCs and paired non-tumor specimens." (PMID 25965583, 2015). "However, whether CTRP6 functions as a general ferroptosis suppressor—by regulating both the SOCS2–xCT/GPX4 and GRP78–MAMs pathways—or acts in a tumor-type–specific manner remains to be determined." (PMID 41228203, 2025). "In lung cancer, CTRP6 promotes tumor proliferation and metastasis, while its knockdown induces ferroptosis via the xCT/GPX4 axis through SOCS2 ubiquitination and degradation, suggesting that targeting CTRP6 could sensitize tumors to ferroptosis-based therapies." (PMID 41228203, 2025). "To determine whether SOCS2 directly mediated the prognosis of HCC after radiotherapy, we randomly selected appropriate tumor tissues from 12 radiosensitive patients and 12 radioresistant patients of HCC for immunofluorescence, and found that radioresistant tissues exhibited lower SOCS2 expression." (PMID 35995846, 2023). "Additionally, PRLR and SOCS2 could promote the expression of phosphoinositide-3 kinase (PI3K) and programmed death ligand 1 (PD-L1), which can protect tumor cells from T cell-mediated immune surveillance, and immune checkpoint blockade (ICB) therapies." (PMID 35739271, 2022). "Together, our data suggest that, in agreement with CA STAT signalling identified using IPA, the GHR pathway may be upregulated in GBMGHR high tumours at several levels: GHR transcription (GHRhigh vs. GHRlow PDCL), GHR protein stabilization and GHR signalling (SOCS2 downregulation)." (PMID 35808822, 2022). "Our study combined WGCNA with differential gene expression analysis, further verified by immune infiltration-type analysis and tumor stemness of microenvironment analysis, and we obtained the survival-related genes IGFBP3 and SOCS2, which may predict the prognosis of HCC." (PMID 33414813, 2020). "However, we succeeded in developing a three-gene signature including UPB1, SOCS2 and RTN3 based on gene-expression profiles of tumor tissue in this study, and fortunately we have validated this model with two independent GEO microarray datasets produced from different platforms." (PMID 28717245, 2017). "The expression of UPB1 was found to be correlated with tumor capsule invaded, and no other significant association was observed between UPB1, SOCS2 and RTN3 expression and clinicopathological variables perhaps partly because of the relatively small sample size." (PMID 28717245, 2017). "Increased expression of SOCS2 in malignancies like chronic myeloid leukemia (CML) could contribute to transformation by negative interference with other SOCS molecules that normally would suppress tumor development." (PMID 24757565, 2014). "The suppressor of cytokine signaling 2 (SOCS2) is a classical negative feedback protein that regulates cytokine signal transduction and has been known to be downregulated in several tumor, but the molecular mechanisms of its involvement in HB metastasis are unknown." (PMID 38071211, 2023). "Interestingly, GH-transgenic mice lacking one copy of SOCS2 show a high incidence in aberrant lesions in the colon indicating that small variations of SOCS2 expression levels can have profound implications on cell proliferation and eventually tumor growth." (PMID 17651480, 2007). "Moreover, IGF1 could not effectively induce EMT and tumour malignant development in SOCS2-overexpressed lung adenocarcinoma cells, further indicating the critical inhibitory role of SOCS2 in the IGF1/IGF1R axis in the EMT and progression of lung adenocarcinoma cells." (PMID 29559623, 2018).